MIR181B2 (microRNA 181b-2)
Synonyms: hsa-mir-181b-2; MIRN181B2; mir-181b-2
Gene: MicroRNA gene on chromosome 9 (124,693,710 to 124,693,798, forward strand). Ensembl gene ENSG00000207737.
Gene Ontology:
Biological process: miRNA-mediated post-transcriptional gene silencing
Cellular component: RISC complex
Homologues: Orthologues: dog MIR181B2 (100% identical), pig ssc-mir-181b-2 (100% identical), chimpanzee ptr-mir-181b-2 (99% identical), macaque mml-mir-181b-2 (99% identical), guinea pig MIR181B2 (93% identical), mouse Mir181b-2 (92% identical), rat Mir181b2 (90% identical), tropical clawed frog xtr-mir-181b-2 (79% identical), zebrafish mir181c (60% identical). Paralogues in human: MIR181B1 (72% identical), MIR181A1 (52% identical), MIR181A2 (49% identical), MIR181C (47% identical).
Diseases named in the same sentence as MIR181B2 in open-access papers:
MIR181B2 is named in the same sentence as 1 disease in open-access papers, as found by Europe PMC text mining. Sharing a sentence is not in itself a finding about the gene and the disease. The quoted sentences say what the papers report.
Insulin resistance (1 paper, 2021). Increased resistance towards insulin, that is, diminished effectiveness of insulin in reducing blood glucose levels. "In accordance with this dose-response of MTX on Mir181b expression, we examined whether the effect of MTX (1 mg/kg) on insulin resistance and adipose tissue inflammation is dependent on Mir181b2 expression in vivo." (PMID 33416495, 2021).